DNAJA2 (DnaJ heat shock protein family (Hsp40) member A2)
Description:
Co-chaperone of Hsc70. Stimulates ATP hydrolysis and the folding of unfolded proteins mediated by HSPA1A/B (in vitro).
Synonyms: Dj3; CPR3; HIRIP4; DNAJ; DNJ3; DJA2; PRO3015; RDJ2
Tractability: PROTAC: UniProt records ubiquitination sites on it; ubiquitination databases record sites on it; its protein half-life has been measured.
Gene: Protein-coding gene on chromosome 16 (46,955,362 to 46,973,704, reverse strand). Ensembl gene ENSG00000069345.
Subcellular location: Membrane
Subcellular location (Human Protein Atlas): Cytosol; Nucleoli
Pathways (Reactome):
Cellular responses to stimuli: HSP90 chaperone cycle for steroid hormone receptors (SHR) in the presence of ligand
Disease: Dengue Virus Genome Translation and Replication
Gene Ontology:
Molecular function: ATPase activator activity; protein binding; protein-folding chaperone binding; ATP binding; heat shock protein binding; Hsp70 protein binding
Biological process: protein refolding; cellular response to heat; positive regulation of cell population proliferation; protein folding; response to heat
Cellular component: cytosol; extracellular exosome; membrane
Genetic constraint (gnomAD): Loss-of-function variants: 6 observed, 45.87 expected, observed/expected ratio (o/e) 0.13, 90% interval 0.071 to 0.26. The upper end of that interval is the gene's LOEUF score, 0.26, which puts it in group 1 of 6, group 1 being the genes least tolerant of losing a copy. Missense variants: 343 observed, 522.97 expected, observed/expected ratio (o/e) 0.66, 90% interval 0.6 to 0.72. Synonymous variants: 159 observed, 177.7 expected, observed/expected ratio (o/e) 0.89, 90% interval 0.79 to 1.02.
Homologues: Orthologues: chimpanzee DNAJA2 (100% identical), macaque DNAJA2 (100% identical), dog DNAJA2 (99% identical), rabbit DNAJA2 (99% identical), mouse Dnaja2 (99% identical), pig DNAJA2 (99% identical), rat Dnaja2 (99% identical), tropical clawed frog dnaja2 (93% identical), zebrafish dnaja2a (86% identical), zebrafish dnaja2b (84% identical), Caenorhabditis elegans dnj-19 (52% identical). Paralogues in human: DNAJA1 (55% identical), DNAJA4 (54% identical), DNAJA3 (28% identical).
Diseases named in the same sentence as DNAJA2 in open-access papers:
DNAJA2 is named in the same sentence as 29 diseases in open-access papers, as found by Europe PMC text mining. Sharing a sentence is not in itself a finding about the gene and the disease. The quoted sentences say what the papers report.
Parkinson disease (2 papers, 2014 to 2025). A progressive degenerative disorder of the central nervous system characterized by loss of dopamine producing neurons in the substantia nigra and the presence of Lewy bodies in the substantia nigra and locus coeruleus. "Thus heat-shock, cigarette smoke, or chemical treatments with elesclomol or the HSP90-inhibitor geldanamycin, as well as in chronically challenged tissues in Parkinson's disease, type II, DNAJB1 and DNAJB4 were found to be systematically more over-expressed than type I, DNAJA1 and DNAJA2." (PMID 25988148, 2014).
autoimmune disease (1 paper, 2022). A disorder resulting from loss of function or tissue destruction of an organ or multiple organs, arising from humoral or cellular immune responses of the individual to their own tissue constituents. "Similarly, in another autoimmune disease, miR-155-3p targets two genes (Dnaja2 and Dnajb1) that negatively regulated Th17 differentiation contributing to potentiate the Th17 response." (PMID 35370692, 2022).
breast carcinoma (1 paper, 2023). "Interestingly, we observed significantly elevated levels of PCM1 and CEP290, but not others in DNAJA2-deficient mouse breast cancer cell line 4T1 and HeLa cells." (PMID 37640708, 2023).
colon cancer (1 paper, 2023). "Similar results were also obtained in DNAJA2-deficient human retinal pigment epithelial-1 (RPE1) cells, lung cancer H460 cells, colon cancer SW620 cells, and DNAJA2-deficient mouse melanoma B16-OVA cells, as compared with their WT controls." (PMID 37640708, 2023).
Glucose intolerance (1 paper, 2025). Glucose intolerance (GI) can be defined as dysglycemia that comprises both prediabetes and diabetes. "Consistently, liver-specific ablation of DNAJA2 induces systemic glucose intolerance and insulin resistance in mice, suggesting that DNAJA2 plays a critical role in maintaining glucose metabolism homeostasis." (PMID 41233317, 2025).
glucose metabolic disorders (1 paper, 2025). "Conversely, DNAJA2 was upregulated in the adipocytes of obese mice compared to lean controls Collectively, these data indicate that dysregulation of DNAJA2 is associated with glucose metabolic disorders, such as T2DM." (PMID 41233317, 2025). "To evaluate the role of DNAJA2 in glucose metabolic disorders, we first analyzed DNAJA2 expression levels from a published dataset (GSE2572425) in human islets isolated from T2DM patients and non-diabetic individuals." (PMID 41233317, 2025).
Insulin resistance (1 paper, 2025). Increased resistance towards insulin, that is, diminished effectiveness of insulin in reducing blood glucose levels. "Here, the authors identify a role for DNAJA2 in regulating insulin signaling and glucose metabolism, loss of which causes insulin resistance and type 2 diabetes phenotypes." (PMID 41233317, 2025). "Mechanistic investigations revealed that DNAJA2 deficiency impairs insulin signaling and induces insulin resistance in mouse models." (PMID 41233317, 2025). "Therefore, our findings provide mechanistic insights into insulin resistance and glucose metabolism, establishing DNAJA2 as a biomarker for T2DM predisposition and pathogenesis." (PMID 41233317, 2025). "The absence of DNAJA2 significantly reduces IR’s plasma membrane localization, causes insulin resistance and disrupts glucose metabolism and homeostasis." (PMID 41233317, 2025). "Conversely, the absence of DNAJA2 significantly reduces the presence of IR on the PM, leads to insulin resistance and disrupts homeostatic metabolism and growth." (PMID 41233317, 2025).
laryngeal carcinoma (1 paper, 2021). Carcinoma that arises from the laryngeal epithelium. "Our data confirmed that RCN1, DNAJA2, LASP1 and IBSP were up-regulated while LAT2, FUZ, HOOK2 and DAPK2 were down-regulated in laryngeal cancer." (PMID 34976784, 2021). "RCN1, DNAJA2, LASP1 and IBSP were up-regulated in laryngeal cancer." (PMID 34976784, 2021).
liver cancer (1 paper, 2025). An epithelial or non-epithelial malignant neoplasm that arises from the liver. "Additionally, we observed a significant decrease in insulin signaling in the liver cancer cell line HepG2 following knockdown of DNAJA2 (SiDJ2), and this effect was consistent when DNAJA2 was knocked out in the mouse syngeneic cancer cell lines 4T1 and MC38." (PMID 41233317, 2025).
melanoma (1 paper, 2023). A malignant, usually aggressive tumor composed of atypical, neoplastic melanocytes. "More strikingly, the data from a melanoma cohort treated with anti-CTLA4 antibody showed that patients with lower levels of DNAJA2 expression were greatly benefitted from the therapy than those with higher levels of DNAJA2 expression." (PMID 37640708, 2023).
Obesity (1 paper, 2025). Accumulation of substantial excess body fat. "In this study, we demonstrate that DNAJA2 dysregulation is associated with metabolic phenotypes, including T2DM and obesity, in humans and mice." (PMID 41233317, 2025). "Analysis of published datasets in humans and mice also reveals that DNAJA2 dysregulation is associated with abnormal glucose metabolic phenotypes, including T2DM and obesity." (PMID 41233317, 2025). "Analysis of public datasets reveals a strong association between DNAJA2 and metabolic phenotypes, including type 2 diabetes mellitus (T2DM) and obesity, in both humans and mice." (PMID 41233317, 2025). "The downregulation of DNAJA2 in islets and its inverse correlation with BMI in T2DM patients, along with its upregulation in adipocytes and hepatocytes in response to obesity and HSD, highlight a complex role of DNAJA2 in glucose metabolism and T2DM pathophysiology." (PMID 41233317, 2025).
Sepsis (1 paper, 2019). Sepsis is defined as life-threatening organ dysfunction caused by a dysregulated host response to infection. "In four of them, the mean abundance was again higher in sepsis than in SIRS, namely, PPP6R3 (1.7-fold), TAX1BP1 (1.5-fold), DNAJA2 (1.8-fold), and ADRBK1 (1.4-fold)." (PMID 31075840, 2019).
cancer (7 papers, 2020 to 2025). A tumor composed of atypical neoplastic, often pleomorphic cells that invade other tissues. "Given that defects in TC-NER cause cancer and premature aging, we predict that deficiency in DNAJA2 could have similar impact on human diseases." (PMID 37907457, 2023). "Given the important role that HSP40 proteins play in protein homeostasis, we hypothesize that DNAJA2 ensures genome stability by regulating cell division and/or DNA repair pathways, and its deficiency modulates genomic instability and cancer immunotherapy." (PMID 37640708, 2023). "Thus, defects in DNAJA2 may cause genomic instability, which can drive cancer development and influence cancer treatment." (PMID 37640708, 2023). "Our study reveals a role for DNAJA2 to regulate mitotic division and chromosome stability and suggests DNAJA2 as a potential target to enhance cancer immunotherapy, thereby providing strategies to advance HSPs-based cancer therapy." (PMID 37640708, 2023). "Our findings provide a strategy for cancer therapy by specifically targeting on DNAJA2, which may advance HSPs-based cancer therapy because of HSP40’s better specificity." (PMID 37640708, 2023). "It has been documented that DNAJA2 plays an important role in cancer development and therapy." (PMID 37907457, 2023). "Consequently, tumors derived from DNAJA2-deficient cancer cells in animal models are highly responsive to the immune checkpoint blockade (ICB) therapy, which correlates with the ICB therapy result observed in cancer patients." (PMID 37640708, 2023). "However, DNAJA2 knockout mice do not develop cancer but exhibit neonatal lethality and the underlying mechanism remains unknown." (PMID 41233317, 2025). "In conclusion, this study uncovers a role of the DNAJA2-CMA axis in maintaining genome stability in human cells and provides strategies to advance the HSPs-based cancer therapy by targeting HSP40s in cancer immunotherapy." (PMID 37640708, 2023). "We therefore conclude that DNAJA2 and CMA components are promising biomarkers and/or targets for enhancing cancer immunotherapy." (PMID 37640708, 2023). "Our results indicate that DNAJA1 and DNAJA2 are functional homologues of yeast YDJ1 and play a role in the protection of cells from cytotoxic stresses such as those exerted by cancer chemotherapeutic agents." (PMID 32149145, 2020). "Both DNAJA2 and CMA confer cancer progression and are required for tumor growth, but the underlying mechanism remains unclear." (PMID 37640708, 2023). "We have extended our investigation by evaluating the role of all human DNAJAs (DNAJA1, DNAJA2, DNAJA3, and DNAJA4) in the response of cells to cancer therapeutic agents, such as doxorubicin, cisplatin, and etoposide, and to define cytotoxic stresses such as ROS and heat shock." (PMID 32149145, 2020). "However, this seems to be in conflict to the data shown in this study, where DNAJA2 knockout mice exhibited neonatal lethality, but had no cancer development." (PMID 41233317, 2025). "Therefore, this study has not only established a role of the HSP40-CMA axis in maintaining mitotic integrity, but also identified DNAJA2 and the CMA pathway factors as potential targets to enhance cancer immunotherapy, providing strategies to advance HSPs-based cancer therapy." (PMID 37640708, 2023).
tumor (5 papers, 2019 to 2025). "Tumor cells depleted of DNAJA2 or CMA factor LAMP2A exhibit elevated levels of centriolar satellite proteins, which causes aberrant mitosis characterized by abnormal spindles, chromosome missegregation and micronuclei formation." (PMID 37640708, 2023). "More strikingly, the DJ2-OE B16-OVA tumors grew much faster than the control tumors after treating with ICB, indicating that DNAJA2 overexpression renders tumor resistance to ICB therapy." (PMID 37640708, 2023). "Tumor cells defective in DNAJA2, HSC70, or CMA factor LAMP2A exhibit abnormal spindles and chromosome segregation errors, which induce aneuploidy and micronuclei." (PMID 37640708, 2023). "Additionally, the proteomic analysis showed an increased protein expression of DNAJA2 in MPN-AITL tumor tissue compared with R-AITL." (PMID 34771688, 2021). "Here, we show that the expression levels of DNAJA2 and CMA factors modulate ICB potency by regulating the type I interferon signaling in tumor microenvironment." (PMID 37640708, 2023). "To evaluate if DNAJA2-deficiency enhances ICB efficacy, we injected WT or DNAJA2-depleted 4T1 or B16-OVA cells subcutaneously into immunocompetent mice, and monitored the tumor growth after treating tumors with or without ICB antibodies." (PMID 37640708, 2023). "Immunohistochemical evaluation of IDH2, DNAJA2 and citrate synthase showed diffuse cytoplasmatic staining of both neoplastic and non-neoplastic cells in the tumor microenvironment in both MPN-AITL and R-AITL samples." (PMID 34771688, 2021).
infection (3 papers, 2008 to 2017). The state of being infected such as from the introduction of a foreign agent such as serum, vaccine, antigenic substance or organism. "For instance, Dnaja2, Dnajb2, Dnajb12a, Dnajb12b, Dnajb14, Dnajc5ab, Dnajc5gb, Dnajc7, Dnajc16, and Dnajc26 were up-regulated only at 3 days after infection, but not at 14 days after infection; similarly, Dnajc28 was up-regulated only at 14 days after infection, but not at 3 days after infection." (PMID 25542027, 2014).
neurodegenerative disease (2 papers, 2023). A disorder of the central nervous system characterized by gradual and progressive loss of neural tissue and neurologic function. "JDPs have previously been implicated in various neurodegenerative diseases, with prior work suggesting that DnaJA2, DnaJB1, and DnaJB4 suppress tau aggregation in vitro." (PMID 37387473, 2023).
metabolic disorders (1 paper, 2025). "In conclusion, our study elucidates the mechanism by which DNAJA2 regulates IR endocytosis, insulin signaling and glucose metabolism, shedding light on the pathogenesis of metabolic disorders." (PMID 41233317, 2025).
DNAJA2 also shares sentences with these, for which no sentence is quoted: vasculitis (2 papers); ANCA associated vasculitis (1); colorectal cancer (1); diffuse large B-cell lymphoma (1); lung carcinoma (1); myeloma (1); neuroblastoma (1); rheumatoid arthritis (1); sarcoma (1); tauopathies (1); type 2 diabetes (1); type 2 diabetes mellitus (1).